WNT11 (Wnt family member 11)
Diseases named in the same sentence as WNT11 in open-access papers (continued):
Sharing a sentence is not in itself a finding about the gene and the disease.
myeloma (1 paper, 2010). "The five remaining genes (NRG2, Wnt4, Wnt11, Wnt16 and FGF18) were considered as a "myeloma MGF" although they were not statistically significantly overexpressed in MMC compared to environment cell populations." (PMID 20465808, 2010).
nephrolithiasis (1 paper, 2015). The presence of a calculus in the pelvis of the kidney; this is most often composed of mineral salts and proteins. "Our study suggested that TGF-β1 and Ca2+ have synergic effects to promote EMT and osteochondral differentiation via Wnt11 and the L-type calcium channel in kidney stone model and corresponding primary renal epithelial cells." (PMID 26193266, 2015).
non-small cell lung carcinoma (1 paper, 2024). A group of at least three distinct histological types of lung cancer, including non-small cell squamous cell carcinoma, adenocarcinoma, and large cell carcinoma. "ATF-2 activated the Wnt/Ca2+ pathway and promoted the expression of Wnt5a, Wnt11, CaMKII and NLK, which regulated the proliferation and invasion of non-small cell lung cancer cells, suggesting that Ca signaling is directly involved in malignant behavior of tumor cells." (PMID 39687904, 2024).
omphalocele (1 paper, 2018). Omphalocele is an embryopathy classified in the group of abdominal celosomias and is characterized by a large hernia of the abdominal wall, centered on the umbilical cord, in which the protruding viscera are protected by a sac. "In our study, downregulation of WNT11, PRKCA and CaMK2D genes after TiO2 NPs treatment (10 μg/ml) possibly interfered with actin-cytoskeleton organization, cell movement and cell adhesion, thus disrupting noncanonical Wnt/Ca2+ signaling that resulted in omphalocele." (PMID 29555972, 2018).
oral cancer (1 paper, 2020). "A recent study revealed a significant association between oral cancer risk and variants in GSK3β (rs9879992) and WNT11 (rs1533767), which are also associated with NSOC risk." (PMID 32143304, 2020).
pancreas cancer (1 paper, 2023). "Heatmap analysis in colorectal, stomach, and pancreas cancer patient datasets showed a consistent overlap between LBH overexpression and WNT signaling genes associated with pathway activation, i.e., WNT2, WNT5A, WNT11, LEF1, TCF4 or TCF7, CCTNB1, CCND1, JUN, DKK3." (PMID 37268816, 2023).
phyllodes tumor (1 paper, 2005). A benign, borderline, or malignant fibroepithelial neoplasm arising from the breast and rarely the prostate gland. "Overexpression of Wnt-5a has been shown to correlate with abnormal nuclear localization of β-catenin protein in phyllodes tumor and ectopic Wnt-11 can rescue axis structures in UV ventralized Xenopus embryos by activation of the Wnt/β-catenin pathway." (PMID 16236168, 2005).
renal agenesis (1 paper, 2025). Renal agenesis (RA) is a form of renal tract malformation characterized by the complete absence of development of one or both kidneys (unilateral RA or bilateral RA respectively), accompanied by absent ureter(s). "Therefore, the SALL4 mutant protein may cause renal agenesis by failing to transcriptionally activate WNT11 and PAX2, thus affecting kidney development." (PMID 40483479, 2025). "This mutation may disrupt the transcription of WNT11 and PAX2, thereby affecting the development and function of fetal kidney ureteric bud cells, ultimately resulting in renal agenesis." (PMID 40483479, 2025).
Situs inversus totalis (1 paper, 2025). "We identified a homozygous human WNT11 variant in an infant with situs inversus totalis, complex heart defects and renal hypodysplasia, and used Xenopus embryos to functionally characterize this variant." (PMID 40200693, 2025).
small cell lung carcinoma (1 paper, 2023). Small cell lung cancer (SCLC) is a highly aggressive malignant neoplasm, accounting for 10-15% of lung cancer cases, characterized byrapid growth, and early metastasis. "For instance, the upregulation of WNT11 observed in small cell lung cancer cell lines was found to be facilitated by the oncogenic transcription factor ASCL1." (PMID 36982422, 2023). "In small cell lung cancer (SCLC), WNT11 has been shown to act on cell proliferation and p38/AKT signaling." (PMID 36982422, 2023).
Tinnitus (1 paper, 2021). Tinnitus is an auditory perception that can be described as the experience of sound, in the ear or in the head, in the absence of external acoustic stimulation. "Together, we thus speculated that rs2846071, or another in LD, may be the variant that has a causal effect on the risk of tinnitus by regulating WNT11 gene expression in brain tissues." (PMID 34482816, 2021). "Further analysis was needed in a larger sample size study to confirm the genetic associations of WNT11 and TNFRSF1A with tinnitus." (PMID 34482816, 2021). "Intriguingly, the newly identified significantly associated genes WNT11 and TNFRSF1A were just in the Wnt and TNF pathways, respectively, therefore highlight the critical roles of these two pathways in the development of tinnitus." (PMID 34482816, 2021). "WNT11 has been reported to involve the formation of cilia, and the abnormality of cilia could influence tinnitus occurrence." (PMID 34482816, 2021). "Together, these pieces of evidence suggested potential roles for WNT11 and TNFRSF1A in the development of tinnitus." (PMID 34482816, 2021). "Here, our eQTL analyses showed that the genotypes of rs2846071 or rs4149577 are correlated with the expression levels of WNT11 or TNFRSF1A, respectively, in multiple brain tissues, suggesting that these two genes may be the candidate genes of tinnitus." (PMID 34482816, 2021). "However, the colocalization analyses showed that the posterior probability of hypothesis 4 (PP4) of rs2846071-WNT11 is less than 0.2 (PP4 = 0.025), indicating that the tinnitus-associated SNP rs2846071 is not colocalized with eQTL signal for WNT11 in brain tissues." (PMID 34482816, 2021).
tongue cancer (1 paper, 2021). A malignant neoplasm affecting the tongue.
cancer (71 papers, 2010 to 2025). A tumor composed of atypical neoplastic, often pleomorphic cells that invade other tissues. "A hypoxia-mediated activation leading to cancer progression was reported for WNT11, the second most up-regulated gene in the CD79B-mutated group." (PMID 41295250, 2025). "The A allele of WNT11 rs15337671 was associated with an increased risk for OPMD/OSCC after adjustment for family history of cancer." (PMID 40960755, 2025). "Wnt-11 levels are associated with cancer stemness, and it is recognized that breast cancer stem cells contributed to tumorigenesis, metastasis and chemotherapeutic resistance." (PMID 33557112, 2021). "Recent studies demonstrated that WNT11 expression is directly co-regulated with ERRα and β-catenin in several cancer cell lines, which is considered the key mechanism underlying the pro-migratory activity of ERRα." (PMID 34089362, 2021). "Members of the WNT signaling pathway, including GSK3β and WNT11, control migration, polarity, and fate during embryonic development and are widely implicated in human cancers." (PMID 32143304, 2020). "Favorable prognosis was observed in patients presenting high expression of “luminal like” genes (AR, GATA3) and decreased survival was observed in patients expressing cancer stem cell-like (WNT11) or EMT-associated genes (MMP28)." (PMID 32708049, 2020). "Previously, WNT11 was shown to be regulated by ERRα in PCa cells and implicated in cancer cell invasion." (PMID 27776343, 2016). "WNT11 has been found upregulated in several cancers, and its expression has been previously associated with increased cell migration." (PMID 22723937, 2012). "Recent study demonstrated that WNT11 expression is directly co-regulated by ERRα and β-catenin in several cancer cells, which is considered as the key mechanism underlying the promigratory activity of ERRα." (PMID 22723937, 2012). "At present, the mechanism(s) underlying the role of Wnt-11 in promoting cancer (including PDAC) cell invasiveness is/are unknown." (PMID 31718047, 2019). "Wnt11 is essential for the development of the heart and kidney, and is also implicated in cancer." (PMID 22715413, 2012). "Investigation of the genetic alteration status of WNT2, WNT7B, and WNT11 in patients with BRCA across various cancer cohorts using cBioPortal has revealed notable insights." (PMID 41044153, 2025). "Conversely, lower expression of WNT11 was observed across individual cancer stages; specifically, stage 2 displayed the lowest expression compared with that in normal tissue." (PMID 41044153, 2025). "Future clinical trials evaluating combination strategies—targeting both immune checkpoints and the WNT11/CAMKII axis—are warranted to fully exploit this new avenue in personalized cancer immunotherapy." (PMID 41426343, 2025). "The upregulated genes, including WNT11, HAPLN1, FGF10, BBOX1, CXADR, NDP, and EREG are associated with tumor proliferation, migration, and cancer stemness." (PMID 35954313, 2022). "The EMT and Wnt-11 pathway was found to be modulated by miR-21 knockout, highlighting the importance of miR-21 as a potential target of cancer stemness." (PMID 35163198, 2022). "Wnt11 activates both canonical and non‐canonical Wnt signalling pathways and plays controversial role in different cancers." (PMID 33417298, 2021). "It has previously been reported that Wnt-11 also plays a significant pathophysiological role in major carcinomas, e.g., cancers of prostate, cervical, ovarian and colon and controls neuroendocrine differentiation." (PMID 31718047, 2019). "The level of Wnt-11 mRNA expression correlates strongly with levels of neuroendocrine differentiation in cancers of the prostate and breast." (PMID 31718047, 2019). "Nevertheless, Wnt11 itself has been reported to be involved in tumor progression of several cancer types." (PMID 28695110, 2017).
cancer (continued). "Taken together, these data suggest WNT11 as a possible target for cancer therapies, especially with tumor hypoxia and/or tumors treated with antiangiogenic therapy." (PMID 26861754, 2016). "Since tumor hypoxia has been proposed to increase tumor aggressiveness, these data suggest WNT11 as a possible target for cancer therapies, especially for tumors treated with antiangiogenic therapy." (PMID 26861754, 2016). "To understand effects of WNT11 on cancer cells, we generated stable overexpression of WNT11 in BT-474 cells, which have amongst the lowest expression of WNT11 in cell lines tested." (PMID 26861754, 2016). "To explore the mechanism underlying the ESRRA mediated regulation of cancer cell proliferation and invasion, we analysed the levels of ESRRA target genes WNT11 and OPN by overexpressing and knocking down its expression." (PMID 26639757, 2015). "A molecular mechanism has been proposed linking ERRα to the activation of Wnt11-elicited pathway leading to increased N-cadherin expression, which is an important mesenchymal biomarker for cancer cells." (PMID 26160845, 2015). "Expression of Wnt11 in human carcinoma cells was significantly increased that induces morphological transformation of intestinal epithelial cells." (PMID 25999350, 2015). "Given that WNT11 has been considered as a key mediator of the promigratory activity of ERRα/β-cat complex in several cancer cell lines including MDA-MB-231, we tested the effect of miR-137 on regulating the expression of WNT11." (PMID 22723937, 2012). "In the present study, we demonstrated that miR-137 decreased the migration/invasion of MDA-MB-231 partly through ERRα-WNT11 pathway, providing an alternative way to inhibit the migration of cancer cells with high migratory capacity." (PMID 22723937, 2012). "Additionally, pan-cancer analysis highlighted the tissue- and tumor-specific expression patterns of WNT2, WNT7B, and WNT11 across various cancers, in agreement with previous studies." (PMID 41044153, 2025). "Furthermore, beyond cancer, WNT11 plays a pivotal role in maintaining hepatic homeostasis and regenerative capacity." (PMID 41426343, 2025). "Similarly, several effector molecules, including CALD1, CDH1, FN1, FZD7, RAC1, STAT3, and WNT11, were downregulated in cancer cells treated with DBMSCs." (PMID 39768220, 2024). "Furthermore, culturing MCTS within RGD-free HAGM cryogels resulted in the highest expression of the genes encoding for VEGF-A, WNT-11, and CD73, involved in angiogenesis, cancer invasion, and tumor growth/metastasis, respectively." (PMID 35198956, 2022). "Therefore, the role of increased EMT markers and Wnt-11 in cancer cells grown within the 3D disease models needs to be further explored." (PMID 35884609, 2022). "Epithelial mesenchymal transition (EMT) marker genes, including Wnt-11, E-cadherin, Vim and Snail expression profiles, were like those seen in real tumour samples, which confirmed that the cancer models were exhibiting real tumour-like characteristics with high fidelity." (PMID 35884609, 2022). "Wnt-11 would thus indeed be a suitable biomarker to validate the 3D cancer models." (PMID 35884609, 2022). "Our previous data indicated both miR-21 and Wnt-11 expression levels are increased in cancer." (PMID 33557112, 2021). "Analysis in relation to conventional prognostic indices of PCa showed a negative correlation with the Gleason grade; Wnt-11 was more frequently found in Gleason 7 grade 4 tumors, suggesting that Wnt-11 perhaps is an important marker during the mid-stage of cancer." (PMID 32182839, 2020). "Wnt family members are known to play regulatory roles in metastasis-related physiological characteristics, such as stemness, EMT, cell differentiation, and invasiveness in malignancies; Wnt-11 mRNA expression correlates strongly with levels of NED in cancers of the prostate and breast." (PMID 32605008, 2020).
cancer (continued). "Moreover, several mRNAs in the ceRNA network were enriched in pathways involved in cancer such as WNT11, FGFR3, PLCB4, and IKBKB." (PMID 31729423, 2019). "More broadly since functional Wnt-11 expression occurs in other cancers as well, its role in determining survival may be more widespread in oncology." (PMID 31718047, 2019). "In addition, fibroblast-derived exosomes can contribute to chemoresistance by increasing the cancer stem cell pool and promote cancer cell invasion through mobilization of Wnt11." (PMID 30925917, 2019). "Wnt-11, a developmentally regulated gene producing a secreted protein, has been associated with various carcinomas but has not previously been studied in PDAC." (PMID 31718047, 2019). "Analysis of patient samples reveals increased levels of FZD8 in cancer, correlating with Wnt-11." (PMID 29717114, 2018). "Wnt-11 promotes cancer cell migration and invasion independently of β-catenin but the receptors involved remain unknown." (PMID 29717114, 2018). "FZD8 and Wnt-11 were also both significantly lower in tumor stroma than in the benign stroma, suggesting that elevated expression in cancer epithelial cells is accompanied by reduced expression in tumor-associated stroma." (PMID 29717114, 2018). "WNT11 has been shown to stimulate the proliferation and migration activity of cancer cells." (PMID 28589081, 2017). "In this manuscript, we further investigated the mechanistic link between WNT11 and cancer." (PMID 26861754, 2016). "This is consistent with recent studies that ERRα can down regulate RHOA stability or induce WNT11 expression to increase cancer cell migration, while knockdown of ERRα during the early stages of zebrafish embryonic development results in inhibition of cell migration." (PMID 26160845, 2015). "In the context of cancer biology, only a limited number of Kaiso target genes have been identified thus far, including the matrix metalloproteinase matrilysin (MMP7), metastasis-associated gene 2 (MTA2), cyclin D1 (CCND1) and Wnt11 (WNT11)." (PMID 25713299, 2015). "Wnt11 promotes cardiac differentiation and a peak of caspase-3/7-like activity induced by Wnt11 was described to be required for P19 carcinoma cell line differentiation to myocytes (e.g. expression of troponin T _tnt_) at least in part through β-catenin degradation." (PMID 26121671, 2015). "Besides, non-canonical WNT pathways, especially the typical WNT5A and WNT11 pathways, are reported to be involved in several carcinogenic and cancer progression pathways." (PMID 23094073, 2012). "Malignant prostate showed stronger expression of Wnt-11 in luminal epithelial cells." (PMID 20219091, 2010). "The logistic regression models evaluating associations between the genetic variants—WNT11 (rs1533767) and AXIN2 (rs3923087 and rs11867417)—and OPMD/OSCC confirmed the allelic associations, suggesting that family history of cancer and smoking habits may act as confounding variables." (PMID 40960755, 2025). "Besides, some studies have demonstrated the significance of WNT11 in other cancers." (PMID 37940644, 2023). "Thus, Wnt-11 seems to play a consistent role in the pathophysiology of cancer." (PMID 31718047, 2019). "The identification of the WNT11/CAMKII signaling axis as an emerging modulator of immune evasion and immunotherapy resistance in LM represents a promising preclinical insight in cancer immunology." (PMID 41426343, 2025). "To investigate the patterns of WNT2, WNT7B, and WNT11 expression in various cancer types, we used TIMER2.0, to explore the expression levels of WNT2, WNT7B, and WNT11 in 33 cancer types and matched normal pairs from the TCGA and GTEx databases." (PMID 41044153, 2025). "Of these, ALDOB, WNT11, MSLN, RAC3, and IL1RN have known roles in CRC, FBLX16 has known roles in other cancers, and SLC38A11 and WBSCR27 are relatively uncharacterized." (PMID 38680862, 2024).